KL (klotho)
Diseases named in the same sentence as KL in open-access papers (continued):
Sharing a sentence is not in itself a finding about the gene and the disease.
mineral bone disorder (9 papers, 2015 to 2024). "At that time, the authors concluded that CKD is a permanent state of Klotho deficiency, and the deficiency of Klotho would be the trigger for the development of bone-mineral disorders in CKD." (PMID 33291777, 2020). "Klotho deficiency is associated with poor clinical outcomes and CKD mineral bone disorders (CKD-MBD)." (PMID 36210812, 2022). "Thus, klotho is associated with CKD and its clinical consequences, including CKD-mineral bone disorder, in dogs." (PMID 32677951, 2020).
renal cell carcinoma (9 papers, 2017 to 2025). "The expression of Klotho protein has been linked to a higher survival rate in patients with renal cell carcinoma." (PMID 37726833, 2023). "Our study suggests that Sohlh2 and DNMT3a/Klotho can be used as potential targets for the clinical treatment of renal cell carcinoma." (PMID 35127476, 2021). "Sohlh2 functions as a tumor suppressor gene in renal cell carcinoma by demethylation of Klotho via DNMT3a." (PMID 35127476, 2021). "In renal cell carcinoma, Sohlh2 was positively correlated with Klotho and negatively correlated with DNMT3a." (PMID 35127476, 2021). "Sohlh2 correlated with Klotho positively and with DNMT3a negatively in renal cell carcinoma." (PMID 35127476, 2021). "Finally, we collected 40 resected renal cell carcinoma samples to study the relevance between Sohlh2, DNMT3a, and Klotho by immunohistochemistry." (PMID 35127476, 2021). "Recent investigation elucidated the low serum level of Klotho in renal cell carcinoma." (PMID 28153033, 2017). "In renal cell carcinoma (RCC) tissue and cell lines, KL protein and mRNA expression are reduced." (PMID 33520985, 2020). "The role of Klotho in renal cell carcinoma (RCC) has been investigated." (PMID 27999207, 2017). "Klotho inhibits pro-tumoral vias, including the PI3K/Akt/GSK3β/Snail pathway, which is important for EMT, an important process in tumor invasion and migration in renal cell carcinoma and other cancers." (PMID 40004457, 2025).
cervical carcinoma (8 papers, 2010 to 2023). A carcinoma arising from either the exocervical squamous epithelium or the endocervical glandular epithelium. "Recent investigations have implicated that Klotho is extensively downregulated in several solid tumors, including cervical cancer, pancreatic cancer, melanoma, and several digestive neoplasm." (PMID 28153033, 2017). "Klotho has been shown to be downregulated in cervical cancer due to epigenetic silencing of the promoter region and its downregulation is associated with cervical cancer invasiveness." (PMID 26356073, 2015). "Functional loss of KLOTHO due to epigenetic silencing may contribute to aberrant activation of the canonical Wnt pathway in cervical carcinoma." (PMID 20482749, 2010). "In this study, we hypothesized that KLOTHO encoding the secreted Wnt antagonist and that acts as a tumor suppressor may be a candidate target for epigenetic silencing in human cervical carcinoma." (PMID 20482749, 2010). "Epigenetic silencing of KLOTHO may occur during the late phase of cervical tumorigenesis, and consequent functional loss of KLOTHO as the secreted Wnt antagonist may contribute to aberrant activation of the canonical Wnt pathway in cervical carcinoma." (PMID 20482749, 2010). "Another study suggests that klotho inhibits the capacity of cell migration and invasion in cervical cancer." (PMID 32614356, 2020). "Similar epigenetic mechanisms of down-regulation of KL expression are effective in human specimens of invasive cervical carcinoma and cell lines." (PMID 33520985, 2020). "Secreted KL acts as a tumor suppressor in CaSki cervical carcinoma cells by inhibiting canonical Wnt signaling and c-MYC and Cyclin D1 expression." (PMID 33520985, 2020). "Overexpression of Klotho in cervical cancer cells upregulates E-cadherin and downregulates N-cadherin, Slug, and Twist." (PMID 26356073, 2015). "This study suggests that transcriptional repression of KLOTHO is correlated with promoter CpG hypermethylation in cervical cancer." (PMID 20482749, 2010). "In this study, we examined epigenetic silencing of KLOTHO in human cervical carcinoma." (PMID 20482749, 2010). "Loss of KLOTHO mRNA was observed in several cervical cancer cell lines and in invasive carcinoma samples, but not during the early, preinvasive phase of primary cervical tumorigenesis." (PMID 20482749, 2010).
Hyperphosphatemic familial tumoral calcinosis (8 papers, 2014 to 2026). "Hyperphosphatemic familial tumoral calcinosis (HTC) is a rare disease caused by autosomal recessive loss of function variants in the genes encoding fibroblast growth factor 23 (FGF-23), Klotho, or GalNAc-T3." (PMID 41675205, 2026). "Hyperphosphatemic familial tumoral calcinosis (FTC) is a rare genetic disorder resulting from the mutations in FGF23, GALNT3, or KL genes." (PMID 34199304, 2021). "Hyperphosphatemic familial tumoral calcinosis (HFTC) is a rare autosomal recessive disorder caused by mutations in FGF23, GALNT3, KLOTHO, or FGF23 autoantibodies." (PMID 33977199, 2021). "Mutations in FGF23, KL, and GALNT3 have been identified as the cause for the development of hyperphosphatemic familial tumoral calcinosis (HFTC)." (PMID 34270404, 2021). "Inactivating autosomal recessive mutations in fibroblast growth factor 23 (FGF23), klotho (KL) and polypeptide N-acetylgalactosaminotransferase 3 (GALNT3) genes lead to a rare disorder, hyperphosphatemic familial tumoral calcinosis (HFTC)." (PMID 30015621, 2019). "Hyperphosphatemic Familial Tumoral Calcinosis (HFTC) and Hyperphosphatemic Hyperostosis Syndrome (HHS) are associated with autosomal recessive mutations in three different genes, FGF23, GALNT3 and KL, leading to reduced levels of fibroblast growth factor 23 (FGF23) and subsequent clinical effects." (PMID 25249269, 2014).
kidney injury (8 papers, 2020 to 2025). Trauma to the kidney. "Using decision trees for classification of patients with a higher or lower risk of AKI we found out that Klotho discriminated between the patients at low risk of developing more severe kidney injury in the first hours after surgery and the patients at high risk better than creatinine." (PMID 33033444, 2020). "During acute kidney injury, both plasma and urine levels of soluble Klotho protein decrease in affected individuals, which was proposed to be a biomarker of the disease." (PMID 34360633, 2021). "Moreover, it was reported that Klotho reduced apoptosis in experimental ischaemic acute kidney injury or renal and cerebral I/R injury." (PMID 32319182, 2020). "This study also showed klotho values were higher in CKD and AKI compared to the control group, showing its role in the pathophysiology of kidney injury." (PMID 41394384, 2025).
renal dysfunction (8 papers, 2019 to 2025). "However, the occurrence of renal dysfunction was associated with an elevation in the urinary excretion of Klotho (3.83 ± 0.24 vs. 2.40 ± 0.10 ng/mL in rats with normal renal function, p < 0.05)." (PMID 38673780, 2024). "Interestingly, the group of animals with renal dysfunction and altered neurobehavioral performance also showed decreased Klotho expression at this level." (PMID 38673780, 2024). "IR injury-induced renal dysfunction was accompanied by an increase in the fractional excretion of Ca2+ and by an impairment in the balance of the fibroblast growth factor 23-klotho-vitamin D axis through down regulation of Klotho expression." (PMID 35155498, 2022). "Moreover, in patients with renal dysfunction, decreased level of circulating Klotho was correlated with brachial-ankle pulse wave velocity which represented arterial stiffness." (PMID 31398214, 2019). "Finally, to elucidate the contribution of Klotho to the prolongation of ventricular repolarization beyond renal dysfunction, we examined ECG parameters in mice hypomorphic for Klotho (kl/kl), which show very high systemic levels of FGF23, and in wild-type (+/+) littermates." (PMID 35042527, 2022).
anemia (7 papers, 2016 to 2024). A reduction in the number of red blood cells, the amount of hemoglobin, and/or the volume of packed red blood cells. "Most of the early as well as current studies have focused on the role of alpha-Klotho in chronic kidney disease (CKD) in elderly populations, and reported an age-related Klotho reduction and association with increased likelihood of anemia." (PMID 38610814, 2024). "Hematocrit was significantly decreased in KL-/- mice, indicating that Klotho deficiency caused anemia." (PMID 29179433, 2017). "Furthermore, the complex interaction between EPO and FGF-23 is discussed, as well as their association with other anemia-related factors and processes such as Klotho, vitamin D, and iron deficiency." (PMID 39684548, 2024). "Here, we investigated whether amelioration of Klotho deficiency by Klotho protein administration can improve anemia in mice with adenine-induced CKD." (PMID 35813388, 2022). "Klotho gene mutation suppressed FGH expression in red blood cells and kidneys resulting in anemia and kidney damage in mice." (PMID 29179433, 2017). "Increased Klotho levels could also potentially contribute to inflammation and anemia reduction in the elderly." (PMID 38610814, 2024). "Another molecule that plays an important role in CKD-MBD is fibroblast growth factor (FGF)-23, whose main role is to maintain serum phosphate levels in the normal range, acting via its co-receptor Klotho; however, its activity may also be related to anemia and inflammation." (PMID 39684548, 2024).
atrial fibrillation (7 papers, 2014 to 2026). A disorder characterized by an electrocardiographic finding of a supraventricular arrhythmia characterized by the replacement of consistent P waves by rapid oscillations or fibrillatory waves that vary in size, shape and timing and are accompanied by an irregular ventricular response. "Association of Klotho levels with the presence of atrial fibrillation." (PMID 24991914, 2014). "The association between Klotho and atrial fibrillation (AF) at baseline was explored as secondary outcome." (PMID 24991914, 2014). "Findings from a clinical study have linked higher Klotho levels to the absence of atrial fibrillation in hemodialysis patients." (PMID 29849175, 2018). "In hemodialysis patients or those undergoing catheter-based percutaneous radiofrequency, Klotho was shown to be protective against atrial fibrillation (AF)." (PMID 41574188, 2025). "We measured heart weight, blood levels of FGF23, Klotho, and mineral metabolism markers, as well as the heart expression of apoptosis proteins (i.e., BAX, Bcl2) and atrial fibrillation (AF)." (PMID 42072635, 2026). "This study investigated the effects of high-intensity interval training (HIIT) and moderate aerobic training (AT) on FGF23, Klotho, mineral metabolism, apoptosis markers (BAX, Bcl2), and atrial fibrillation (AF) in a rat CKD model." (PMID 42072635, 2026). "Regression analysis for Klotho tertiles with the absence of atrial fibrillation." (PMID 24991914, 2014).
Cerebral ischemia (7 papers, 2017 to 2025). Restriction of arterial blood supply to the brain associated with insufficient oxygenation to support the metabolic requirements of the tissue. "SIRT1-driven deacetylation predominates in diabetic HIIT, irisin-Klotho signaling in cerebral ischemia, and canonical PI3K/AKT phosphorylation in systemic inflammation." (PMID 40861274, 2025). "Conversely, the neuroprotective effects of irisin were lost in klotho knockout mice, suggesting the role of klotho in mediating irisin action in cerebral ischemia mouse model." (PMID 41373506, 2025). "Exercise-induced irisin enhances cognition in a mouse model of cerebral ischemia by upregulating the expression of klotho, a protein that helps in controlling insulin sensitivity, MnSOD, and FOXO3a, and reduces ROS generation." (PMID 41373506, 2025). "Klotho was also proposed as a novel therapeutic target for cerebral ischemia, due to its antioxidative effect through AKT/FOXO1 pathway." (PMID 37985893, 2023). "In the present study, we also used a rat model of transient focal cerebral ischemia to explore the potential role of Klotho in the resistance to cerebral ischemia." (PMID 29403373, 2017). "The present results suggest that Klotho overexpression in the brain significantly ameliorated neuroinflammatory neuropathological changes after cerebral ischemia." (PMID 29403373, 2017). "In a mouse model of cerebral ischemia, voluntary wheel running increased myokine irisin; irisin, in turn, upregulated the longevity protein Klotho, permitting nuclear FoxO3a accumulation and MnSOD transcription, thereby quenching reactive oxygen species and improving cognition." (PMID 40861274, 2025). "In addition, when mice subjected to cerebral ischemia, their cognitive function was impaired, the protein expressions of klotho, MnSOD, and FOXO3a downregulated, and the production of reactive oxygen species (ROS) increased compared with the sham group." (PMID 34306305, 2021). "To explore the influence of Klotho on ischemic stress, we evaluated neurobehavioral function and body weight in lentivirus-treated 2VO mice every 24 h during a 72 h observation period after the onset of brain ischemia." (PMID 29403373, 2017). "Our present study demonstrated that the neuroprotective effects of physical exercise and exogenous irisin on cerebral ischemia were the same, and irisin could prevent mortality and improve cognitive dysfunction after cerebral ischemia through upregulating the expression of klotho." (PMID 34306305, 2021). "Thus, we explored whether exogenous irisin exerted neuroprotective effects on cerebral ischemia by regulating klotho expression." (PMID 34306305, 2021). "All these results suggested that the neuroprotective effects of irisin on cerebral ischemia were compromised with the absence of the klotho gene." (PMID 34306305, 2021). "The present results suggest that Klotho may effectively inhibit RIG-I/IL-6-induced inflammation, likely through both NF-κB-dependent and -independent mechanisms that are involved in brain ischemia." (PMID 29403373, 2017).
cerebrovascular diseases (7 papers, 2018 to 2025). "A cross-sectional study proposed that age and smoking are risk factors for cardiovascular and cerebrovascular diseases, while Klotho is a protective factor." (PMID 40007807, 2025). "The results showed that serum klotho (HR(95%CI) = 0.975(0.960–0.990), p = 0.001) and age (HR(95%CI) = 1.104(1.038–1.174), p = 0.002) were the independent risk factors of cerebrovascular disease in hemodialysis patients." (PMID 30791885, 2019). "In Chinese, the relationship between genetic variants of klotho and cerebrovascular disease needs to be explored." (PMID 30791885, 2019). "The present study shows that decreased serum klotho concentration is the independently risk factor of cerebrovascular disease." (PMID 30791885, 2019). "Klotho, as an aging-suppressor gene, contributes to protect on vascular calcification and oxidative stress, which are the risk factors of cerebrovascular disease." (PMID 30791885, 2019). "The serum klotho level was significantly associated with cerebrovascular disease in hemodialysis patients (HR(95%CI) = 0.975(0.960–0.990), p = 0.001)." (PMID 30791885, 2019). "It is hypothesized that decreased serum klotho protein is the novel risk factor of cerebrovascular disease in hemodialysis patients." (PMID 30791885, 2019). "Genetic variants of klotho have been associated with cerebrovascular disease." (PMID 30791885, 2019). "The purpose of the present study is to determine the relationship between serum klotho and cerebrovascular disease in patients receiving hemodialysis." (PMID 30791885, 2019). "Based on the strong vascular-protective effects of klotho, the current study aimed to confirm the relationship between serum klotho and cerebrovascular disease in patients receiving hemodialysis." (PMID 30791885, 2019). "The present study is the first to show that serum klotho as a potential predictor of cerebrovascular disease in hemodialysis patients." (PMID 30791885, 2019). "Future studies will be required to confirm the importance of the klotho SNP in the development of cerebrovascular disease." (PMID 30595559, 2018). "The FGF23/klotho axis is a key participant in CKD-MBD and is closely related to vascular calcification and cerebrovascular diseases." (PMID 34759797, 2021). "Therefore, decreased klotho protein could be a novel non-traditional risk factor for cerebrovascular disease in hemodialysis patients." (PMID 30791885, 2019). "As compared to the patients without cerebrovascular disease, serum klotho level was significantly lower in the participants with cerebrovascular disease (91.65 ± 28.19 pg/ml versus 131.90 ± 49.09 pg/ml, P = 0.000)." (PMID 30791885, 2019).
coronary artery calcification (7 papers, 2018 to 2025). Calcification of the coronary artery, used as a measure of coronary atherosclerosis, a risk factor for myocardial infarction. "In addition, increasing evidence has shown that a lower Klotho concentration is an independent predictor of all-cause and cardiovascular mortality and can accelerate coronary artery calcification in patients on maintenance hemodialysis." (PMID 38409304, 2024). "Several studies reported that reduced serum Klotho levels might be a risk factor for coronary artery calcification in CKD patients 40,41." (PMID 38993571, 2024). "It was reported that circulating Klotho levels were inversely correlated with coronary artery calcification in patients with CAD." (PMID 35197934, 2022). "We aimed to investigate the relationship between serum soluble Klotho protein (sKlotho) level and coronary artery calcification (CAC) as well as prognosis in patients with maintenance hemodialysis (MHD)." (PMID 29900135, 2018). "This study was to investigate the role of serum Klotho, fetuin-A, and Matrix Gla Protein (MGP) in Coronary Artery Calcification (CAC) in patients with Maintenance Hemodialysis (MHD) and their predictive value for CAC." (PMID 39089098, 2024).
ischemic stroke (7 papers, 2017 to 2023). A stroke disorder caused by obstruction of blood flow to the brain, due to thrombotic (local blood clot formation) or embolic (due to a blood clot or other material traveling from another site) event. "The cerebrospinal concentrations of irisin and klotho from ischemic stroke patients were measured with an enzyme-linked immunosorbent assay (ELISA)." (PMID 34306305, 2021). "Moreover, Klotho has been identified as a genetic risk factor for ischemic stroke that is caused by cardioembolism in Korean females." (PMID 29403373, 2017). "Additionally, a recent study showed that Klotho gene overexpression significantly decreased IL-6 production in HUVECs with or without inflammatory challenge, and IL-6 receptor polymorphisms contributed to neurological status in ischemic stroke patients." (PMID 29403373, 2017). "We conducted a pilot human study to establish the relationship between the CSF irisin concentration and the CSF klotho concentration in ischemic stroke patients." (PMID 34306305, 2021). "Our study demonstrated that plasma Klotho concentration was negatively associated with the presence, burden and progression of cerebral SVD in patients with first-ever ischaemic stroke." (PMID 31398214, 2019). "In particular, samples from ischemic stroke patients showed an increase in circulating CD106+ (+83.4%), CD31+ (+3.1%), CD171+ (+5.1%), Ephrin B+ (+21.5%) and CD11b+ (+21.8%) EVs, whereas we observed a decrease in the circulating IB4+ (−6.6%) and Klotho+ (−10.7%) compared to control subjects." (PMID 37175644, 2023).